ADIPOR1 (adiponectin receptor 1)
Description:
Receptor for ADIPOQ, an essential hormone secreted by adipocytes that regulates glucose and lipid metabolism. Required for normal glucose and fat homeostasis and for maintaining a normal body weight. ADIPOQ-binding activates a signaling cascade that leads to increased AMPK activity, and ultimately to increased fatty acid oxidation, increased glucose uptake and decreased gluconeogenesis. Has high affinity for globular adiponectin and low affinity for full-length adiponectin (By similarity).
Synonyms: PAQR1; TESBP1A; CGI-45; ACDCR1; CGI45
Tractability: Small molecule: a structure with a bound ligand is known. Antibody: UniProt places it where antibodies can reach, with high confidence; its Gene Ontology location is reachable by antibodies, with high confidence; UniProt predicts a signal peptide or a membrane-spanning region. PROTAC: ubiquitination databases record sites on it; its protein half-life has been measured; a small molecule that binds it is known.
Target class: Membrane receptor
Gene: Protein-coding gene on chromosome 1 (202,940,090 to 202,958,572, reverse strand). Ensembl gene ENSG00000159346.
Subcellular location: Cell membrane
Pathways (Reactome):
Metabolism: AMPK inhibits chREBP transcriptional activation activity
Gene Ontology:
Molecular function: adipokinetic hormone receptor activity; adiponectin binding; protein binding; protein kinase binding; signaling receptor activity; identical protein binding
Biological process: adiponectin-activated signaling pathway; fatty acid oxidation; hormone-mediated signaling pathway; negative regulation of epithelial cell migration; negative regulation of epithelial to mesenchymal transition; negative regulation of non-canonical NF-kappaB signal transduction; negative regulation of receptor signaling pathway via JAK-STAT; positive regulation of lipid catabolic process; glucose homeostasis; positive regulation of cold-induced thermogenesis; regulation of glucose metabolic process; regulation of lipid metabolic process; leptin-mediated signaling pathway; negative regulation of cell growth; positive regulation of insulin receptor signaling pathway; positive regulation of receptor signaling pathway via JAK-STAT
Cellular component: membrane; plasma membrane
Genetic constraint (gnomAD): Loss-of-function variants: 14 observed, 38.33 expected, observed/expected ratio (o/e) 0.37, 90% interval 0.24 to 0.57. The upper end of that interval is the gene's LOEUF score, 0.57, which puts it in group 2 of 6, group 1 being the genes least tolerant of losing a copy. Missense variants: 284 observed, 500.59 expected, observed/expected ratio (o/e) 0.57, 90% interval 0.51 to 0.63. Synonymous variants: 173 observed, 182.81 expected, observed/expected ratio (o/e) 0.95, 90% interval 0.83 to 1.07.
Homologues: Orthologues: chimpanzee ADIPOR1 (100% identical), macaque ADIPOR1 (99% identical), guinea pig ADIPOR1 (98% identical), rat Adipor1 (97% identical), mouse Adipor1 (97% identical), pig ADIPOR1 (96% identical), dog ADIPOR1 (93% identical), tropical clawed frog adipor1 (87% identical), zebrafish adipor1a (82% identical), zebrafish adipor1b (75% identical), Drosophila melanogaster AdipoR (52% identical), Caenorhabditis elegans paqr-1 (47% identical), and 1 more. Paralogues in human: ADIPOR2 (69% identical), PAQR3 (25% identical), PAQR8 (19% identical), PAQR5 (18% identical), PAQR7 (18% identical), PAQR6 (17% identical), PAQR9 (17% identical), PAQR4 (16% identical), MMD2 (13% identical), MMD (12% identical).
Diseases named in the same sentence as ADIPOR1 in open-access papers:
ADIPOR1 is named in the same sentence as 200 diseases in open-access papers, as found by Europe PMC text mining. Sharing a sentence is not in itself a finding about the gene and the disease. The quoted sentences say what the papers report.
Obesity (77 papers, 2008 to 2025). Accumulation of substantial excess body fat. "It is known that obesity, IR, and T2D are associated with a downregulation of the gene encoding AdipoR1." (PMID 39997710, 2025). "It is likely that obesity-associated downregulation of AdipoR1 expression within the SM contributes towards a diminished response of the SM to adiponectin, which in turn contributes towards IR." (PMID 39997710, 2025). "AdipoR1 and R2 are downregulated in type 2 diabetes and obesity, causing a decrease in cardiac adiponectin signaling, reducing cardiac protection against cardiac remodeling and lipotoxicity." (PMID 35890325, 2022). "In our model, the obesity condition associated with aging determines an upregulation of AdipoR1, with a consequent increase of the AMPK active form in adipose tissue." (PMID 33255520, 2020). "The objective of this work was to analyze the expression of AdipoR1 and AdipoR2, modulated by differential concentrations of leptin in an obesity model (10 ng/mL, 100 ng/mL, and 1000 ng/mL) associated with breast cancer in MCF-7 and HCC1937 cell lines." (PMID 29311755, 2017). "This chromosome region harbors the adiponectin receptor 1 gene, which has been previously associated with obesity." (PMID 18854016, 2008). "Interestingly, our results show that significantly higher ADIPOR1 levels were associated with a more aggressive breast tumour only in postmenopausal women with obesity." (PMID 41456223, 2025). "Therefore, after identification of AdipoR1 and AdipoR2 as the primary acting receptors which are downregulated in obesity-associated IR and diabetes, one study reported that overexpression of AdipoR1 in skeletal muscle of rats improved glucose uptake." (PMID 37239098, 2023). "CR, with the achievement of normal weight and the rise of both AdipoR1 and pAMPK, significantly inhibited NFκB expression and consequently suppressed the proinflammatory state, which appears to be more linked to obesity than aging." (PMID 33255520, 2020). "In fact, obesity-linked insulin resistance and diabetes down-regulate AdipoR1 expression." (PMID 28963462, 2017). "Therefore, ADIPOR1 is a potential candidate gene for pleiotropic effects on obesity and diabetes susceptibility in humans." (PMID 18854016, 2008). "Thus, the overexpression of AdipoR1 in the liver of a mouse model of human obesity caused an increase in the activation of the AMPK pathway, while the overexpression of AdipoR2 caused an increase in the expression of peroxisome proliferator activated receptor alpha (PPAR-α) target genes." (PMID 34860303, 2022). "Thus, we next evaluated whether the AdipoR1 expression in lung Tregs was associated with the grade of obesity." (PMID 33256137, 2020). "In our study using ZDF rats as model of obesity and diabetes type II, AdipoR1 protein expression was significantly suppressed by metabolic disorders, which was further accentuated by the administration of QCT." (PMID 39576482, 2025). "Protein content of adiponectin receptor 1 (AdipoR1) in ScWAT was significantly reduced by obesity (p < 0.05) as well as by QCT administration (p < 0.05)." (PMID 39576482, 2025). "Adiponectin receptor 1 (AdipoR1), the predominant receptor isoform in skeletal muscle, is suppressed in obesity and Type 2 diabetes." (PMID 40641114, 2025). "Downregulating Adipor1 demonstrated the value of these extracts in managing obesity, particularly Pineapple, which inhibited the gene by 10-fold vs. −2.10-fold in Southern Home-treated adipocyte cells." (PMID 38931172, 2024). "On the other hand, it has been shown that decreased adiponectin serum levels and increased AdipoR1 and AdipoR2 expression occur in response to the development of diet-induced obesity in mice." (PMID 37240258, 2023). "That means adiponectin is related to both obesity and cognitive decline via AdipoR1 and AdipoR2 receptors." (PMID 37363537, 2023).
Obesity (continued). "The obesity-related gene phosphatase and tensin homolog was a direct target of miR-216a, which regulates expression of adiponectin receptor 1, caveolin-1, caveolin-2, and PPARγ." (PMID 35711801, 2022). "In obesity, adiponectin resistance is increased with reduced expression of adiponectin receptors (ADIPOR1 and ADIPOR2) in breast cancer cells." (PMID 34367982, 2021). "measured miRNAs in whole breast milk that target mRNA of leptin (LEP), adiponectin (ADIPOQ) and their respective receptors (LEPR, ADIPOR1 and ADIPOR2) which are associated with obesity." (PMID 33801634, 2021). "Our previous studies generated transgenic AdipoR1 mice and found these mice defend against obesity, hepatosteatosis, and insulin resistance when fed a high-fat high-sucrose diet." (PMID 33477525, 2021). "Accordingly, our group previously showed that AdipoR1 expression in Helios+ Tregs negatively correlated with epididymal fat in a mouse model of diet-induced obesity (DIO)." (PMID 34084174, 2021). "These AdipoR1-derived mouse mesenchymal stem cell transplantations ameliorate obesity-induced hepatosteatosis." (PMID 33477525, 2021). "Airway allergic inflammation in lean mice also resulted in a reduced expression, while for airway allergic inflammation combined with obesity, the AdipoR1 expression followed the obesity pattern." (PMID 33256137, 2020). "Using models of DIO and airway allergic inflammation, we showed that obesity resulted in a reduction in the AdipoR1 expression." (PMID 33256137, 2020). "In conclusion, we demonstrated that Tregs in the lungs expressed AdipoR1, which was modulated by obesity and allergic inflammation, and that airway eosinophilia increased with excessive weight gain." (PMID 33256137, 2020). "For instance, PTBP cooperates with miR-221 to regulate the translation of AdipoR1 (Adiponectin receptor protein 1) mRNA during muscle differentiation and in obesity." (PMID 31741723, 2019). "We also identified nominally significant associations between ADIPOR1 rs10920533 and total cholesterol and ADIPOR2 rs11061971 and obesity risk." (PMID 30816311, 2019). "The expression of AdipoR1 is regulated by many factors; obesity, alcohol, and insulin resistance can lower while exercise, stress, and cerebral ischemic conditions can increase the levels of AdipoR1." (PMID 30060752, 2018). "Collectively, these results identify overlapping effects of AdipoR1 and AdipoR2 as well as additional, distinct effects of the latter that provide a foundation for further investigations aimed at reducing obesity-related complications." (PMID 28145500, 2017). "AdipoR1 disruption in mice led to obesity and impaired insulin resistance with elevated levels of tissue triglycerides, inflammation, and oxidative stress." (PMID 27763537, 2016). "Obesity also decreases adiponectin sensitivity by downregulating the expression of AdipoR1 and AdipoR2 adiponectin receptors, which in turn leads to insulin resistance." (PMID 27881129, 2016). "Increasing the expression levels of AdipoR1 and AdipoR2 in the liver of mouse models of obesity and type 2 diabetes can improve insulin resistance and diabetes." (PMID 24490657, 2014). "Polymorphisms in adiponectin-related genes (ADIPOQ, ADIPOR1, ADIPOR2) have been examined for relationships with obesity, insulin resistance and diabetes, cardiovascular disease, and to circulating adipokine levels, but many gaps in knowledge remain." (PMID 24586568, 2014). "We suggest that these differences reflect the isoform-specific ability to activate AMPK in adipocytes and the distribution of AdipoR1 and AdipoR2 receptors which is modified by obesity." (PMID 23805277, 2013). "Mice deficient for either or both receptors were glucose intolerant, and adenovirus mediated expression of AdipoR1 and AdipoR2 in liver improved obesity-related insulin resistance and T2DM in db/db mice through AMPK and PPARα pathways, respectively." (PMID 21943112, 2011).
Obesity (continued). "Another group concluded that the adiponectin level is inversely correlated with obesity, diabetes and insulin resistance, whereas the amounts of adipoR1/R2 mRNA increased in muscle in a compensatory effect." (PMID 18353182, 2008). "Besides, ADIPOR1 levels were higher in breast adipose tissue adjacent to the tumour of postmenopausal women and obesity, with a more aggressive breast tumour." (PMID 41456223, 2025). "We hypothesized that the tumour microenvironment (TME) of the breast had lower levels of ADIPOQ and ADIPOR1 in postmenopausal women with obesity than in those with a normal BMI." (PMID 41456223, 2025). "Assuming a paracrine effect of adiponectin, the up-regulated adiponectin/AdipoR2 system in ScWAT in obese rats may represent a compensatory mechanism against insulin resistance and down-regulated AdipoR1 by obesity." (PMID 39576482, 2025). "However, AdipoR1 declines in aging, obesity, and T2DM,430 weakening beneficial adiponectin signaling to alleviate the disruptive effects of metabolic diseases." (PMID 39764565, 2025). "In the current literature on the upstream activation proteins of AMPK and PPARα, it is well-established that adiponectin binds to adiponectin receptors AdipoR1 and AdipoR2 and exerts anti-lipid effects in obesity via activation of AMPK and PPARα pathways, respectively." (PMID 40176148, 2025). "ADIPOR1 levels were higher in breast tumour tissue compared to breast adipose tissue adjacent to the tumour in both postmenopausal women with normal BMI or with obesity." (PMID 41456223, 2025). "We hypothesized that breast tumor tissue has higher ADIPOQ and ADIPOR1 levels compared to adjacent adipose tissue in postmenopausal women with obesity versus those with a normal BMI." (PMID 41456223, 2025). "Our data suggested that activating adiponectin/AdipoR1 signaling might be one of the therapeutic targets for obesity-induced male infertility." (PMID 38459078, 2024). "In this study, we showed that testicular adiponectin/AdipoR1 signaling was decreased in obesity." (PMID 38459078, 2024). "Studies suggested that adiponectin could correlate with obesity and dementia as AdipoR1 and AdipoR2 suppression promotes neurodegeneration." (PMID 37363537, 2023). "AT inflammation in obesity exacerbates allergic inflammation by downregulating lung AdipoR1+ Tregs." (PMID 36051916, 2022). "Adipor1 and Adipor2 are known to be downregulated in obesity-related insulin resistance." (PMID 35804799, 2022). "More recently, we showed that severe obesity augmented the frequency of AdipoR1+ Tregs in lungs, suggesting that adipose tissue-related Tregs might reach distant tissues to control systemic inflammation." (PMID 34084174, 2021). "For instance, adiponectin levels and AdipoR1/R2 expression levels are both decreased in obesity." (PMID 34084174, 2021). "Here, we aimed to determine whether Helios+ and Helios− Treg subsets expressed AdipoR1 in the lungs of obese mice and whether different obesity grades affected the expression upon allergic lung inflammation." (PMID 33256137, 2020). "Tregs are critical in limiting immune activation and inflammation in allergic diseases and asthma; however, it is unknown if subsets of Tregs in the lung express AdipoR1 and if the expression is altered by obesity and pulmonary allergic inflammation." (PMID 33256137, 2020). "The adiponectin receptor 1 (ADIPOR1) gene encodes a seven transmembrane protein named for its purported cognate ligand adiponectin, a secreted hormone that is inversely correlated with development of obesity, insulin resistance, and type 2 diabetes." (PMID 30254279, 2018). "AdipoR1 is ubiquitously expressed in obesity-related cancers." (PMID 28178338, 2017). "Additionally, the adiponectin level and ADIPOR1/ADIPOR2 expression are reduced in obesity and obesity-related diseases and likely contribute to the characteristic low-grade inflammation because of the absence of the anti-inflammatory effects of adiponectin." (PMID 26147005, 2015).
Obesity (continued). "ADIPOR1 variants have been associated with type 2 diabetes, pre-diabetes states and measures of obesity although not in all studies." (PMID 18854016, 2008). "Moreover, we observed higher ADIPOR1 levels only in breast adipose tissue adjacent to the tumour in postmenopausal women with obesity and tumour size > 2.0 cm and clinical stage II/III (p = 0.019 and p = 0.025, respectively) versus postmenopausal women with a normal BMI." (PMID 41456223, 2025). "However, we found that ADIPOR1 protein levels were higher in breast tumour tissue than in adjacent breast adipose tissue in both postmenopausal women with normal BMI and those with obesity." (PMID 41456223, 2025). "Therefore, liver AdipoR1 expression shows sexual dimorphism, which may reflect the enhanced availability for adiponectin (a ligand) and protection against diet-induced obesity in female mice." (PMID 36810096, 2023). "Effective treatment is yet to be found; although in T2DM and obesity, adiponectin was reported to be a cardioprotective adipokine that is downregulated, adiponectin signaling is also impaired due to the downregulation of both receptors (AdipoR1 and R2), leading to reducing cardio protection." (PMID 35890325, 2022). "Investigations of how AdipoR1 signaling influences 5-HT neuron activity and transmission will reveal new insights into our understanding of mood disorders, especially those conditions that are comorbid with obesity and type 2 diabetes involving adipose tissue dysfunction and hypoadiponectinaemia." (PMID 31980728, 2021). "Therefore, obesity is thought to lead to decreases not only in plasma adiponectin levels but also in AdipoR1/R2 expression, thereby reducing adiponectin sensitivity and inducing insulin resistance, which, in turn, leads to hyperinsulinemia thus resulting in a “vicious cycle”." (PMID 31475160, 2019). "Collectively, these results demonstrate that AdipoR1 and AdipoR2 exhibit overlapping and distinct effects in skeletal muscle consistent with enhanced adiponectin sensitivity but these appear insufficient to ameliorate established obesity-induced adiponectin resistance." (PMID 28145500, 2017). "In mouse models of obesity, both PTB and miR-221 are upregulated in muscle and liver tissues, contributing to the pathological decline in AdipoR1 protein." (PMID 40732992, 2025). "Studies using AdipoR1 knockout mice showed decreased AMPK activity, while AMPK activity correlated with adiponectin levels in an obesity model." (PMID 37770988, 2023). "The findings of the study demonstrated that BCP reduced obesity-related AHR by inhibiting macrophage polarisation, activating AMPK, activating Nrf2/HO-1, increasing AdipoR1 and AdipoR2 expression, and decreasing NFB expression in the lungs of animals." (PMID 37251328, 2023). "In this sense, the adiponectin receptors AdipoR1 and AdipoR2 (which, like OR83B, have an inverted membrane topology) are decreased in animal models of obesity and type 2 diabetes." (PMID 34860303, 2022). "Hence, it is possible that gAd/AdipoR1 axis may exert a protective role against inflammatory conditions, such as obesity, where the upregulation of AdipoR1 through its own ligand may increase the sensitivity of Tregs to adiponectin, which in turn promotes IL-10 production." (PMID 34084174, 2021). "AdipoRon is an oral AdipoR1/R2 agonist that successfully reestablished adiponectin functions, mainly activating AMPK and PPAR-α pathways, in obesity-related type 2 diabetes." (PMID 31052147, 2019). "Random glucose levels were unaffected by either overexpression of AdipoR1 and AdipoR2 or HFD-induced obesity." (PMID 28145500, 2017). "Besides, the ADIPOR1 rs1539355 could highlight the role of ADIPOQ SNPs in obesity genotype." (PMID 22087284, 2011). "In muscle, the expression levels of ADIPOR1 and ADIPOR2 correlated positively with obesity, glucose and insulin levels and insulin resistance." (PMID 21943112, 2011).